CCND1 (cyclin D1)
Description:
Regulatory component of the cyclin D1-CDK4 (DC) complex that phosphorylates and inhibits members of the retinoblastoma (RB) protein family including RB1 and regulates the cell-cycle during G(1)/S transition. Phosphorylation of RB1 allows dissociation of the transcription factor E2F from the RB/E2F complex and the subsequent transcription of E2F target genes which are responsible for the progression through the G(1) phase. Hypophosphorylates RB1 in early G(1) phase. Cyclin D-CDK4 complexes are major integrators of various mitogenenic and antimitogenic signals. Also a substrate for SMAD3, phosphorylating SMAD3 in a cell-cycle-dependent manner and repressing its transcriptional activity. Component of the ternary complex, cyclin D1/CDK4/CDKN1B, required for nuclear translocation and activity of the cyclin D-CDK4 complex. Exhibits transcriptional corepressor activity with INSM1 on the NEUROD1 and INS promoters in a cell cycle-independent manner.
Synonyms: BCL1; PRAD1; U21B31; D11S287E
Tractability: Small molecule: a drug acting on it is in phase 2 or 3 trials; a high-quality ligand is known; it belongs to a druggable protein family. PROTAC: UniProt records ubiquitination sites on it; ubiquitination databases record sites on it; a small molecule that binds it is known.
Target class: Other cytosolic protein
Safety:
Unwanted effects reported when the protein is acted on. In parentheses: how it was acted on, where the effect was seen, and who reports it.
drug toxicity (source: ClinPGx)
Gene: Protein-coding gene on chromosome 11 (69,641,143 to 69,654,474, forward strand). Ensembl gene ENSG00000110092.
Subcellular location: Nucleus; Cytoplasm; Nucleus membrane
Subcellular location (Human Protein Atlas): Nucleoplasm
Pathways (Reactome):
Gene expression (Transcription): RUNX3 regulates WNT signaling; RUNX3 regulates p14-ARF; Regulation of RUNX1 Expression and Activity; Transcriptional Regulation by VENTX; Transcriptional regulation by RUNX2
Cell Cycle: Cyclin D associated events in G1; Drug-mediated inhibition of CDK4/CDK6 activity; SCF(Skp2)-mediated degradation of p27/p21; Ubiquitin-dependent degradation of Cyclin D
Signal Transduction: Estrogen-dependent gene expression; Estrogen-dependent nuclear events downstream of ESR-membrane signaling; PTK6 Regulates Cell Cycle; Pre-NOTCH Transcription and Translation
Immune System: Interleukin-4 and Interleukin-13 signaling; SPOP-mediated proteasomal degradation of PD-L1(CD274)
Chromatin organization: RMTs methylate histone arginines
Developmental Biology: Regulation of MITF-M-dependent genes involved in cell cycle and proliferation
Disease: Defective binding of RB1 mutants to E2F1,(E2F2, E2F3)
Gene Ontology:
Molecular function: cyclin-dependent protein serine/threonine kinase activator activity; enzyme binding; histone deacetylase binding; proline-rich region binding; protein binding; protein kinase binding; protein serine/threonine kinase activator activity; transcription corepressor activity; cyclin-dependent protein serine/threonine kinase regulator activity; kinase activity; protein kinase activity; protein-containing complex binding
Biological process: DNA damage response; G1/S transition of mitotic cell cycle; mitotic G1 DNA damage checkpoint signaling; negative regulation of transcription by RNA polymerase II; positive regulation of G2/M transition of mitotic cell cycle; response to leptin; response to UV-A; response to xenobiotic stimulus; positive regulation of G1/S transition of mitotic cell cycle; animal organ regeneration; cellular response to hypoxia; Leydig cell differentiation; liver development; positive regulation of cell population proliferation; positive regulation of mitotic cell cycle phase transition; regulation of G1/S transition of mitotic cell cycle; regulation of transcription by RNA polymerase II; response to calcium ion; response to corticosterone; response to estradiol; response to estrogen; response to ethanol; response to glucocorticoid; response to iron ion; response to magnesium ion; and 3 more
Cellular component: cyclin D1-CDK4 complex; cyclin D1-CDK6 complex; cyclin-dependent protein kinase holoenzyme complex; cytoplasm; nuclear membrane; nucleoplasm; nucleus; transcription repressor complex; cytosol; microtubule organizing center; bicellular tight junction
Genetic constraint (gnomAD): Loss-of-function variants: 10 observed, 27.88 expected, observed/expected ratio (o/e) 0.36, 90% interval 0.22 to 0.61. The upper end of that interval is the gene's LOEUF score, 0.61, which puts it in group 2 of 6, group 1 being the genes least tolerant of losing a copy. Missense variants: 335 observed, 405.07 expected, observed/expected ratio (o/e) 0.83, 90% interval 0.75 to 0.9. Synonymous variants: 194 observed, 171.48 expected, observed/expected ratio (o/e) 1.13, 90% interval 1.01 to 1.27.
Cancer hallmarks: invasion and metastasis (promotes); genome instability and mutations (promotes); invasion and metastasis (suppresses); change of cellular energetics (promotes)
Homologues: Orthologues: chimpanzee CCND1 (100% identical), guinea pig CCND1 (97% identical), dog CCND1 (95% identical), pig CCND1 (95% identical), mouse Ccnd1 (94% identical), rat Ccnd1 (94% identical), macaque CCND1 (81% identical), tropical clawed frog ccnd1 (78% identical), zebrafish ccnd1 (76% identical), Drosophila melanogaster CycD (38% identical), Caenorhabditis elegans cyd-1 (26% identical), Caenorhabditis elegans cya-1 (23% identical), and 9 more. Paralogues in human: CCND2 (62% identical), CCND3 (52% identical), CCNA2 (25% identical), CCNA1 (24% identical), CCNJ (23% identical), CCNE2 (22% identical), CCNE1 (21% identical), CCNJL (21% identical), CCNO (21% identical), CCNB1 (20% identical), CCNF (20% identical), CCNB2 (20% identical), and 6 more.
Diseases named in the same sentence as CCND1 in open-access papers:
CCND1 is named in the same sentence as 663 diseases in open-access papers, as found by Europe PMC text mining. Sharing a sentence is not in itself a finding about the gene and the disease. The quoted sentences say what the papers report.
breast cancer (1,604 papers, 1995 to 2026). A primary or metastatic malignant neoplasm involving the breast. "One of the key ER target genes is CCND1, encoding Cyclin D1, which is consistently overexpressed in ER+ breast cancers and plays a central role in maintaining sustained CDK4/6 activation." (PMID 41596432, 2026). "PRMT2 regulates breast cancer progression as well, the loss of the protein leading to increased cyclin D1 expression, resulting in cancer progression." (PMID 40869229, 2025). "Preclinical data have implicated cyclin D1/CDK4 in resistance to therapy in HER2+ breast cancer and the potential of CDK4/6i to overcome this resistance, providing rationale for the investigation of abemaciclib in combination with HER2-targeted therapy." (PMID 40144206, 2025). "CCND1 amplification is known to be a driving event in breast cancer, but contradictory findings are reported for its association with prognosis." (PMID 39586971, 2025). "Overexpression of Cyclin D1 is associated with the development of various cancers, including breast cancer, prostate cancer, and pancreatic cancer." (PMID 40170854, 2025). "In breast cancer, there is also an association between CCND1 amplification and elevated proliferation, high histopathological grade, and the Luminal B subtype." (PMID 40940829, 2025). "In a cohort of 62 HER2-positive breast cancer patients from a clinical trial, higher CCND1 gene copy number was significantly associated with reduced rates of achieving a pathological complete response to neoadjuvant chemotherapy plus trastuzumab." (PMID 39806366, 2025). "CDK4 and cyclin D1 overexpression has been reported to cause resistance to CDK4/6 inhibitors in breast cancer cells." (PMID 39123441, 2024). "It has also been reported that elevated expression of the CCND1 gene is associated with an increment in the resistance of breast cancer tumors to hormone therapies." (PMID 38850382, 2024). "Analysis of Top2A, Top2B, and cyclin D1 expression in 2254 human breast cancer samples showed cyclin D1, and TOP2A co-expression was associated with ERα+ tumors." (PMID 38191593, 2024). "It was previously reported that CCND1 overexpression is associated with better outcomes for patients with breast cancer but its overexpression is linked to TAM resistance." (PMID 38246945, 2024). "PI3Kca mutation in hormone receptors and breast cancer has been identified as a causative factor for the subsequent modification of cyclin D1 and Rb protein." (PMID 39539450, 2024). "Cyclin D1 is a key oncoprotein that promotes the proliferation of cancer cells and is linked to tamoxifen resistance in breast cancer." (PMID 39439957, 2024). "An association between the cyclin D1 overexpression and therapeutic response to drugs, such as tamoxifen in breast cancer patients and combined chemotherapy of erlotinib and bexarotene in lung cancer patients, was identified in clinical studies." (PMID 37894399, 2023). "Some studies have indicated that the overexpression of cyclin D1 or CDK4 caused tumor in mice, while knockout cyclin D1 or CDK4 caused resistance to the development of murine breast cancer." (PMID 36838737, 2023). "Among 5 screened target genes for miR-410-3p (HMGB1, STAT3, IRS1, SOX2, and CCND1), the oncogene encoding cyclin D1 (CCND1) had the most expression level in breast cancer tissues." (PMID 37310654, 2023). "More large retrospective studies are warranted to rigorously investigate the role of endocrine resistance markers (ERBB2, BCL2, and CCND1) in screening FA patients with a high recurrence risk and increased risk of breast cancer." (PMID 37328469, 2023). "CCND1 is associated with luminal breast cancers and amplifications have been found in chemoresistant post-treatment ER+ tumors." (PMID 37190123, 2023). "CCND1 overexpression is found in more than 50% of human breast cancers and causes mammary cancer in transgenic mice." (PMID 36927310, 2023).
breast cancer (continued). "In a recent study examining cyclin D1 in breast cancer, the amplification of CCND1 was associated with increased risk of disease recurrence, whereas a higher expression of cyclin D1 protein was associated with decreased recurrence risk." (PMID 36675501, 2023). "Preclinical studies have shown that increased expression of RB and cyclin D1 and deletion of p16 are associated with the effects of palbociclib on breast cancer, lymphoma, sarcoma, and other tumors including lung cancer." (PMID 35463335, 2022). "Upregulation of cyclin D1 expression and RB phosphorylation and activation of the mTOR signaling pathway have been associated with resistance in ER + breast cancer." (PMID 36229710, 2022). "Cyclin D1 is overexpressed primarily in luminal breast cancer (luminal A and luminal B) associated with ERα+ breast cancer." (PMID 36358806, 2022). "It has been reported that cyclin D1 and D3 are critical for the growth of breast cancer cells in vitro and in vivo, with loss of cyclin D3 resulting in compensatory upregulation of cyclin D1." (PMID 35406445, 2022). "STAT3 is a transcription factor for breast cancer proliferation-associated genes such as CCND1, c-myc, BCL2, and BAX." (PMID 36106139, 2022). "ER + breast cancer frequently demonstrates gain of CCND 1 (cyclin D1) and CDK4 and loss of CDKN2A (p16) and CDKN2C (p18)." (PMID 36229710, 2022). "FGFR2 has been suggested to be implicated in breast cancer as a target for therapeutic strategies, CCND1 is frequently mutated by copy number variation and suggested as a prognostic biomarker." (PMID 35267517, 2022). "We previously showed that in extracranial models of HER2 + breast cancer, resistance to HER2-targeted therapy in HER2 + breast cancer is mediated by upregulation of cyclin D1 and CDK4, thus, susceptible to CDK4/6 inhibition." (PMID 35304445, 2022). "Increased CCND1 copy number (CN) in breast cancer (BC) is associated with high histopathological grade, high proliferation, and Luminal B subtype." (PMID 35459982, 2022). "While ERα is the primary oncogenic driver in ER+ breast cancer cancers, other genetic alterations such as cyclin D1 overexpression in 50% of breast cancers and CDKN2A loss, contribute to disease progression and therapeutic response." (PMID 33741974, 2021). "Recently, high-throughput sequencing of breast and ovarian tumours revealed that common oncogene amplifications (i.e. CCND1 encoding cyclin D1 in breast cancer and CCNE1 encoding cyclin E in ovarian cancer) rarely occur in tumours with BRCA1/2 gene mutations." (PMID 34389725, 2021). "The Kaplan–Meier plotter has explained that high expression of CCND1 is associated with less survival rate of breast cancer patients." (PMID 33438725, 2021). "Unsurprisingly, ER+ breast cancer that is resistant to endocrine therapy is often associated with CCND1 overexpression and Rb phosphorylation." (PMID 34771508, 2021). "In this research study, the comprehensive search was performed to collect all the SNPs of CCND1 that are associated with breast cancer by GWAS." (PMID 33438725, 2021). "EGR1 has been implicated in the inhibition of cell cycle progression in breast cancer through transcriptional repression of cyclin D1, D2, and D333,34." (PMID 33436746, 2021). "While there was no statistical evidence which reveals the association of PR and HER2 with DFM with expression of Cyclin D1 in patients with breast cancer." (PMID 33438725, 2021). "The ABCSG Trial 05 and 06 documented an increased expression of cyclin D1, which was associated with the poorer clinical outcome and shorter overall survival of breast cancer patients." (PMID 33920506, 2021). "It has been reported that abnormally expressed cyclin D1 was associated with multiple cancers, such as pancreatic cancer, non-small-cell lung carcinoma, breast cancer, head and neck squamous cell carcinoma, endometrial cancer, and colorectal carcinoma." (PMID 34434893, 2021).
breast cancer (continued). "Approximately 35% of ERα+ breast cancers demonstrated amplification of CCND1 gene (encoding cyclin-D1), and about 16% demonstrated amplification of the gene that encodes CDK4." (PMID 33498407, 2021). "Between the top mRNAs with anti-correlated expression to miR-193 we identified, the CCND1 to be associated with cell proliferation as a direct target in melanoma, prostate, ovarian and even in breast cancer." (PMID 33461524, 2021). "According to the GWAS, it was also found that among different cancers CCND1 has highest association with breast cancer." (PMID 33438725, 2021). "The loss of PRMT2 nuclear expression in breast cancer cells is linked to increased cyclin D1 expression via indirectly binding to the AP-1 site on the cyclin D1 promoter, thus promoting breast tumor cell proliferation." (PMID 34833139, 2021). "GSK3β inactivation stabilizes β-catenin expression, induces its translocation to the nucleus, upregulates the downstream target CCND1 gene (encoding cyclin D1), and promotes breast cancer stem cell (BCSC) function and mammary tumor development." (PMID 34403222, 2021). "CCND1 is one of the most commonly overexpressed genes in human BC and causes mammary tumors in transgenic mice." (PMID 34211974, 2021). "Levels of CDK4 and Cyclin D1, both of which are important molecular markers associated with cell-cycle progression, decreased following AG-205 treatment in both breast cancer cell lines." (PMID 32704174, 2020). "A different amplicon based at locus 11q13 contains the gene CCND1 encoding for cyclin D which is implicated in hormonal therapy resistance in breast cancer and is targeted therapeutically by inhibitors of cyclin-dependent kinases." (PMID 32987805, 2020). "In the present study, the inhibition of de novo protein synthesis by CHX notably shortened the half-life of Cyclin D1 in the 2 SHP2 knockout breast cancer cell lines, thus indicating that SHP2 loss resulted in rapid degradation of Cyclin D1." (PMID 32944401, 2020). "In contrast, studies found that increased levels of cyclin D1 expression was associated with positive prognosis in breast cancer." (PMID 32697404, 2020). "Cyclin D1 is one of the most important oncoproteins that drives cancer cell proliferation and associates with tamoxifen resistance in breast cancer." (PMID 33139730, 2020). "In spite of this low mutation rate, Wnt signaling is activated in over 50% of breast cancer and is associated with enhanced cyclin D1 expression and tumor progression and reduced overall survival." (PMID 32210163, 2020). "Previous studies found that high CCND1 expression and amplification associates with an impaired response to tamoxifen treatment and high risk of relapse in luminal breast cancer." (PMID 32410585, 2020). "Differing from Socs1, Cyclin D1 is overexpressed in more than 50% of breast cancer, encoding the regulatory subunit of a holoenzyme that phosphorylates the gene retinoblastoma (RB) and promotes G1/S cell cycle progression and oncogenesis." (PMID 32631271, 2020). "In agreement, our results indicated that MET increased the level of p‐APMK in drug‐resistant and drug‐sensitive breast cancer cells, and also reduced the levels of other proteins associated with cell proliferation (cyclin D1 and PCNA)." (PMID 32281270, 2020). "Overall, we confirmed E2F1 and CCND1 were two direct targets of miR-93, and proved high expression of E2F1 and CCND1 were positively associated with chemoresistance of breast cancer." (PMID 32796817, 2020). "The miR-34a overexpression in the MCF-7 (p = 0.006) and MDA-MB-231(p = 0.002) breast cancer cells was significantly associated with the decreased mRNA expression of CCND1 gene in vitro." (PMID 32660221, 2020). "In a tissue microarray of 50 ERα-positive breast cancers examined, membrane-associated cyclin D1 was detected in four cases." (PMID 32948740, 2020). "It has been reported that cyclin D1 overexpression causes breast cancer and has an inverse relationship with survival." (PMID 32405344, 2020).